IL10 (interleukin 10)
Diseases named in the same sentence as IL10 in open-access papers (continued):
Sharing a sentence is not in itself a finding about the gene and the disease.
colitis (continued). "Together, our results suggested that Wogonin significantly increased the IL-10 production and enhanced the therapeutic effects of MSCs in DSS-induced colitis." (PMID 34239686, 2021). "A previous study has demonstrated that the production of cytokines such as IL-1ɑ, IL-6, IL-10, and IFN-γ are significantly reduced in mice with enhanced STAT3 activity during DSS-induced colitis." (PMID 33673239, 2021). "Several researches supported that IL-10 is highly relevant to IBD, and IL-10−/− mice would spontaneously develop colitis." (PMID 34239686, 2021). "In a study where 3% DSS (40 kDa) was administered for 7 days to induce acute colitis in C57BL/6 mice, serum TNF-α levels were quite high compared to control group, while IL-10 levels decreased in the colitis group." (PMID 31999939, 2020). "The knockout mice for IL-10 (IL-10 -/-) are used in intestinal inflammation disease (DII) studies, as they develop colitis spontaneously and affect the discontinuous ones that affect the entire extension of the small and large intestine." (PMID 33376496, 2020). "Similar to IL-10, IL-22 exerts a protective effect on mucosal inflammation in most animal models, but plays a harmful role in the anti-CD40-induced colitis model, which will be discussed later in this section." (PMID 32670290, 2020). "Remarkably, compelling evidence has shown that the level of the anti‐inflammatory cytokine IL10 is increased after probiotic treatments (e.g. Lactobacillus GG, VSL#3, and Akkermansia) in animal models of colitis, consistent with our findings." (PMID 32363766, 2020). "B. fragilis PSA induces the differentiation of IL-10 producing FoxP3+ Tregs in mice in a TLR2-dependent manner, which can protect against TNBS-induced colitis and experimental colitis induced by Helicobacter hepaticus." (PMID 32351514, 2020). "We found that Ts-EVs dramatically reduced the expression of pro-inflammatory cytokines, whereas the levels of anti-inflammatory cytokines like IL-10 and TGF-β increased significantly in colon tissue of mice with TNBS-induced colitis." (PMID 32595641, 2020). "Curcumin decreased the expression of Th1 cytokines (IL-12, IFN-γ, TNF-α) and increased that of Th2 cytokines (IL-4 and IL-10) in colon mucosa and thereby exerted therapeutic effects on TNBS-induced colitis." (PMID 32153570, 2020). "L. curvatus exerts some probiotic effects, such as mediating the production of IL-10 by dendritic cells through NF-κB and extracellular regulated protein kinases (ERK) signals to relieve colitis in mice." (PMID 32993033, 2020). "Another study showed that two weeks of RJ administration led to changes in the serum levels of IL-1β, IL-10, and TNF-α in a rat model of colitis." (PMID 33050250, 2020). "LRCs induced multiple members of the IL-10 cytokine family, including DC-derived IL-10, and ILC3-derived IL-22, and provided protective effects in a murine colitis model." (PMID 33101234, 2020). "In IL-10 knockout mice and DSS-induced colitis models, VDR exhibited protective effect on intestinal structure and barrier function." (PMID 32541827, 2020). "Human-derived 17 strains of Clostridium species induce Foxp3+CD4+Treg through IL-10, TGF-β1, butyrate and inducible T cell costimulatory (ICOS), and prevent mucosal inflammation in several murine colitis models." (PMID 31482438, 2020). "TPC immunomodulates by stimulating colon anti-inflammatory cytokines (IL-10) and by downregulating pro-inflammatory cytokines (IL-1β, IL-17, and TNF-α) in collagen-induced arthritis model and DSS-induced colitis model." (PMID 32486445, 2020). "Our data suggested that Wogonin impeded IL-10 production from LPS-treated B cells in vitro and weakened the immunoregulatory effect of B cells on DSS-induced murine colitis." (PMID 32566686, 2020). "Pretreatment of colitis mice with L. reuteri I5007 significantly reduced the DSS-induced production of TNF-α, IL-6, IFN-γ, and IL-17A, as well as increased the level of IL-10 compared with the DSS group." (PMID 32751784, 2020).
colitis (continued). "The results also showed that treatment with LP-YS4 significantly reduced the serum concentrations of ET-1, SP, and IL-10 while significantly increasing those of SS, VIP, and IL-2 in colitis mice (P < 0.05)." (PMID 32849906, 2020). "A highly prevalent gut anaerobe, Faecalibacterium prausnitzii, and its culture supernatant decreased TNF-α and increased IL-10 secretion in mice with 2,4,6-trinitrobenzenesulphonic acid (TNBS)-induced colitis." (PMID 33281770, 2020). "SLPI administration has been shown to be more effective than IL-10 and TGF-β at preventing intestinal inflammation in a colitis animal model." (PMID 33199802, 2020). "The results indicated that SSP inhibited pro-inflammatory factors (as IL-6, IL-17A, IL-23, and TNF-α) and improved IL-10 expression, or restrained TGF-β1 in the colonic tissue of colitis mice." (PMID 32581849, 2020). "This in turn enables chitin digestion and the generation of small sized chitin particles that drive IL-10 production via TLR-9 sensing, promoting the attenuation of colitis and C. glabrata elimination." (PMID 32661259, 2020). "The first attempt in the use of TAT-GILZ was performed in a mouse model of DNBS-induced colitis, in which TAT-GILZ treatment successfully reduced the severity of spontaneously developed colitis in IL-10-knock-out mice." (PMID 33584696, 2020). "Functionally, Tfh cells are divided into Tfh1, Tfh2, Tfh10, Tfh17, Tfh21, and Tfr cell lineages, which respectively produce or express interferon (IFN)-γ, IL-4, IL-10, IL-17, IL-21, and forkhead box (FOX)P3, and these are closely related to colitis." (PMID 32581849, 2020). "Acute murine colitis was induced using 4% DSS and chronic colitis was generated in piroxicam-treated IL-10-/- mice." (PMID 33233771, 2020). "Local application of CS-IGF-1C hydrogel with hP-MSCs significantly ameliorates mouse colitis via PGE2, which polarizes M2 macrophages and upregulates IL-10 secretion." (PMID 32685014, 2020). "CBC (0.001–1 μM) exhibited promising anti‐inflammatory effects in an in vitro model of colitis, decreasing LPS increased nitrite levels and attenuating IFN‐γ and IL‐10 secretion in peritoneal macrophages." (PMID 32608035, 2020). "As a consequence, the IL10/IL12 ratio, which has been reported as an indicator for in vivo performance in a mouse colitis model, is significantly lower in lgt mutant than the wild-type, implying a more pro-inflammatory profile after exposure to the mutant." (PMID 32849426, 2020). "Next, they gavaged SPF IL-10−/− mice TC, glycocholic acid, or control PBS and found significantly increased severity of colitis in the TC group only." (PMID 32133003, 2020). "IL‐10 and TGF‐β1 have been reported to down‐regulate immune response in animal models of various diseases including inflammatory bowel disease, colitis, tumours and diabetes." (PMID 31880383, 2020). "PGN purified from Lactobacillus salivarius Ls33, a strain that has protective effects in colitis, induces IL-10-producing DCs in a NOD2-dependent manner in vitro and protects mice from colitis in an IL-10-dependent manner." (PMID 32719681, 2020). "Of the tested bacteria, HP2, which most potently inhibited IL-10 expression, also suppressed HFD-induced bodyweight gain, liver steatosis, and colitis most effectively." (PMID 31986244, 2020). "For instance, in both rat methotrexate-colitis and LPS-treated IEC-6 models, curcumin decreases levels of TNF-α and IL-1β, as well as increases levels of the anti-inflammatory cytokine, IL-10." (PMID 31003422, 2019). "B. adolescentis IF1-03 stimulated macrophage maturation to produce higher levels of IL-10 and lower levels of IL-6 and TGF-β, consistent with the upregulation of Treg cells in DSS-colitis mice in vivo, and splenocytes in vitro." (PMID 30987344, 2019). "A multitude of studies have been performed in mouse models of IBD, the two most-commonly used being IL-10 knockout mice and dextran sulfate sodium (DSS)-induced colitis." (PMID 30863410, 2019).
colitis (continued). "Previous reports showed that in an animal model of colitis, mice treated with CTX present an up regulation of local anti-inflammatory cytokines, such as TGF-β and IL-10, and a decreased expression of proinflammatory cytokines, such as IL-6 and TNF-α." (PMID 31757011, 2019). "IL-10−/− were exposed to CSC in specific pathogen-free conditions, which induce IL-10−/− mice to spontaneously develop local colitis and mild inflammation from the 8th week of age, as described in previous studies." (PMID 31608070, 2019). "TGP were also shown to attenuate TNBS-induced colitis in rats by decreasing up-regulated pro-inflammatory cytokines TNF-α and IL-1β, and increasing down-regulated anti-inflammatory cytokine IL-10." (PMID 31461974, 2019). "The sedentary mice fed HFD with experimental colitis presented significantly higher colonic tissue content of TNF-α, IL 1β, IL-6, IL-17, INFγ, and IL-10 as compared with the respective values of these cytokines recorded in sedentary mice fed SD (p < 0.05)." (PMID 31117199, 2019). "In dextran sulfate sodium salt-induced colitis, intestinal lamina propria macrophages expressing MGL1 increase IL-10 production in response to commensal Streptococcus bacteria, playing a protective role against autoimmune colitis." (PMID 31248427, 2019). "Compared to GPR68+/+/IL-10−/− mice (a mouse model of spontaneous colitis), GPR68−/−/IL-10−/− mice have a lower incidence and delayed onset and progression of rectal prolapse, implicating a role for GPR68 in promoting experimental inflammatory bowel disease." (PMID 30696114, 2019). "On the other hand, the presence of anti-inflammatory cytokines, such as IL-10, suggests a decreased serum value, in different data, consistent with the expected inflammatory process instigated by TNBS induced colitis." (PMID 31581545, 2019). "EPHX2 tool inhibitors have been reported to inhibit colitis and ulcer formation in dextran sodium sulfate (DSS)-induced, and in IL10 (interleukin 10) knockout mouse IBD models." (PMID 31002701, 2019). "In a mouse model of murine colitis models, GAG therapy also improved the inflammatory reaction and induced IL-1Ra and IL-10 production." (PMID 30667338, 2019). "When colitis mice were treated with SASP and MRS (10 ml/kg), the anti-inflammation status was improved by increasing the mRNA level of IL-10 compared with that in the AA group." (PMID 31182999, 2019). "In mice, either genetic deficiency of EPHX2 or treatment with a tool EPHX2i have been reported to attenuate chronic active IBD in IL10 (-/-) and in DSS-induced colitis models." (PMID 31002701, 2019). "It was confirmed by increased histopathology of colitis, goblet cell dysfunction, colonic dilatation and wall thickening, and increased serum levels of inflammatory cytokines (TNF-α and IL-10)." (PMID 31437166, 2019). "Consistent with the worsened colitis, DKO mice had significantly increased intestinal permeability (2.7 ± 0.6 ng/min) compared to IL10−/− mice (1.1 ± 0.2 ng/min)." (PMID 29849494, 2018). "These ASC-induced macrophages were characterized by high arginase I activity, IL-10 production and expression of LIGHT, heme oxygenase (HO)-1 and arginase II, possessing immunomodulatory capacity in vitro and in experimental colitis and sepsis." (PMID 29559912, 2018). "Lactobacillus curvatus WiKim38 induces IL-10 production in dendritic cells and alleviates DSS-induced colitis in mice." (PMID 30369917, 2018). "In a murine T-cell transfer or TNBS model of colitis, expression of IL-1β, IL-6, tumor necrosis factor alpha (TNF-α), and IL-10, which are involved in inflammation, was regulated by B. fragilis." (PMID 30429227, 2018). "IL10 KO and IL2 KO mice spontaneously develop colitis when raised under conventional conditions by dysregulated immune responses against commensal bacteria." (PMID 30333822, 2018).
colitis (continued). "We also noted that colonic levels of pro-inflammatory cytokines, such as INF-γ, IL6, IL1-β, TNF-α, and IL10, were significantly (P < 0.001) increased in mice with DSS-induced colitis, as compared to healthy mice." (PMID 28528363, 2018). "Two mouse models were used to evaluate the impact of S. Typhimurium infection: the chemical induction of colitis by dextran sulfate sodium (DSS) and interleukin (IL)-10−/− mice, which develop spontaneous intestinal inflammation." (PMID 29896196, 2018). "Similar to the findings for PSA and B. fragilis, curli fibers (amyloid fibers in enteric biofilms) are recognized by TLR2, result in IL-10 production, and ameliorate TNBS-induced colitis." (PMID 29515999, 2018). "Along the same line, HSD-fed mice presented increased intestinal inflammation in IL-10−/− mice and increased severity of Dextran Sulfate Sodium (DSS)- and 2,4-Dinitrobenzene Sulfonic Acid (DNBS)-induced colitis." (PMID 30697217, 2018). "In addition, compared with IL10-deficient mice, IL10-deficient/mast cell-deficient double-knockout mice (DKO mice) exhibit increased colitis and associated colonic pathophysiology indicating that in spontaneous colitis models, mast cells may be protective." (PMID 29849494, 2018). "Compared with IL10−/− mice, DKO mice exhibited more severe colitis as assessed by increased colitis scores, mucosal hypertrophy, intestinal permeability, and colonic cytokine production." (PMID 29849494, 2018). "And mono-inoculation of this pathobiont in germfree IL10−/− mice fed with milk fat diet can even induce TH1 immune response and colitis development." (PMID 29090023, 2017). "IL-10 induced differentiation of CD4 T cells into type 1 regulatory T (Tr1) cells and prevented colitis induced in severe combined immunodeficient (SCID) mice by pathogenic CD4 + CD45RB (high) splenic T cells." (PMID 28455817, 2017). "Bulgaricus) was demonstrated as an effective therapy in both murine IL-10−/− colitis and trinitrobenzenesulphonic acid (TNBS) induced colitis through enhancement of IL-10 and TGF-β expressing T cells." (PMID 28529928, 2017). "Increased levels of IL-10 are observed in the plasma of IBD patients and in the colon of rats with DSS-induced colitis; IL-10 attenuates the exaggerated inflammatory response." (PMID 28030847, 2017). "IL-9-producing type I NKT cells protect against DSS-induced colitis through IFN-γ and IL-17A suppression, as well as IL-10 and TGF-β upregulation, depending on IL-4 production by type I NKT cells." (PMID 28095507, 2017). "We also reported the involvement of IL-10 and showed that DKT prolonged the survival time of mice with DSS-induced colitis." (PMID 28210268, 2017). "Here, a significant reduction of IL-10 production by Bcl-3TOE CD4+ T cells was found, probably contributing to the observed colitis phenotype in Bcl-3TOE mice." (PMID 28452361, 2017). "Oral administration of antioxidative enzyme-producing gm-CRL807 and WT-CRL807 to mice markedly potentiated the ratio of IL-10-positive:IL-17-positive cells, a ratio that had been reduced by TNBS administration, and provided amelioration of colitis." (PMID 28179904, 2017). "Moreover, GW9662 weakened the downregulation of Th17 cell-specific cytokine expression and the upregulation of IL-10 expression by madecassic acid in the colons and diminished madecassic acid-induced upregulation of Foxp3 expression and protection against colitis." (PMID 28358365, 2017). "HdAg has been shown to relieve DSS-induced colitis, with decreased expression of IFN-γ, IL-17, and TNF and increased expression of IL-10." (PMID 29163443, 2017). "In 2011, an immunobiotic strain, B. longum NCC2705 (NCC2705), was engineered to secrete biologically active IL-10, and the strain’s curative effects in DSS colitis were investigated." (PMID 28179904, 2017). "In this study, we showed that oral administration of Hsp65-LL prevented colitis development in mice and induced CD4+Foxp3+/CD4+LAP+ Tregs in a TLR2/IL-10-dependent fashion." (PMID 28194152, 2017).
colitis (continued). "Oral administration of LL-LcrV significantly enhanced colonic IL-10 production in a TLR-2-dependent manner and was able to prevent and improve colitis in two different mouse models." (PMID 29387056, 2017). "Our results were similar to those of previous studies indicating that intestinal bacterial induces IL-10 activation and expression through TLR/nuclear factor-κB signaling mainly in mucosal immune cells to involve colitis." (PMID 28683149, 2017). "One cytokine induced in DCs exposed to ΔprtX was the anti-inflammatory IL-10, which has been proposed as a biological therapy for chronic irritable bowel disease (IBD), including Crohn’s disease and colitis." (PMID 28713337, 2017). "In colon tissues of PBS-treated mice with colitis, the mRNA expression levels of TNF-α, IL-1β, IFN-γ, and IL-17 were considerably increased, whereas that of IL-10 was only slightly increased." (PMID 28701721, 2017). "lactis prevented the reduction of IL-10 in the colonic tissue, which was critical for the immunoregulatory effect induced by the Hsp65-LL in the DSS colitis model." (PMID 28194152, 2017). "Compared with normal rats, the levels of many cytokines including IL-6, TNF-α, IL-17, IL-23, IL-1βand IFN-γ were increased, while IL-13, IL-10 and IL-4 were decreased in TNBS-induced colitis rats." (PMID 29113344, 2017). "Ameliorates TNBS-induced colitis in mice, decreases production of pro-inflammatory cytokines (IFN-γ and IL-17), and increases production of regulatory cytokines (IL-10 and TGF-β) in colon tissue." (PMID 29163443, 2017). "After transformation, recombinant probiotic strains were induced with nisin in order to either express IL-10 or TGF-β and orally administered to mice suffering from colitis." (PMID 28491143, 2017). "Moreover, Flavell and colleagues have shown that Th17 cells are also able to differentiate into IL-10-producing Tr1 cells during the resolution of inflammation and that this population of Tr1 cells present regulatory properties as they abolished Th17 cell-mediated colitis." (PMID 27322617, 2016). "The neutralization of IL-10 abrogated the inhibitory effect of MS both in macrophages and in endotoxic shock, bacteria-induced sepsis, CLP and DSS-induced colitis models, suggesting the requirement for IL-10 in the protective effect of MS." (PMID 27405597, 2016). "Intragastric administration of L. lactis MG1363 FnBPA+ (pValac::dts::IL-4) was able to decrease the severity of colitis, with animals showing decreased levels of IL-12, IL-6 and MPO activity; and increased levels of IL-4 and IL-10." (PMID 27576902, 2016). "To better understand the mechanism by which AMT-E ameliorates the DSS-induced colitis, we assessed the colonic production of the inflammatory cytokines TNF-α and IL-1β and the anti-inflammatory cytokine IL-10." (PMID 27527191, 2016). "These macrophages also express arg-1, PD-L1, and PD-L2, promote IL-10 production in CD4+ T cells in a cell contact–dependent manner, and protect against allergy and colitis upon adoptive transfer." (PMID 27101372, 2016). "These in vitro results were further supported by analysis of IL-10 levels in mice following endotoxin shock, mice with bacteria-induced sepsis, CLP mice and mice with DSS-induced colitis." (PMID 27405597, 2016). "To convince the role of IL-10 producing CD8+ T cells for immune regulation, we investigated colitis following depletion of CD8+ T cells using three times treatment of anti-CD8 antibody." (PMID 26908454, 2016). "For the anti-inflammatory cytokines, including IL-10, IL-13, TGF-β, a slight increase was observed in TNBS-induced colitis, which was consistent with previous work." (PMID 27544348, 2016). "In accordance, mice that underwent TNBS-induced colitis followed by adrenalectomy had a marked increase in IFN-γ and IL-10 levels in serum." (PMID 27403034, 2016).